SELENBP1 (selenium binding protein 1)
Diseases named in the same sentence as SELENBP1 in open-access papers (continued):
Sharing a sentence is not in itself a finding about the gene and the disease.
cancer (43 papers, 2008 to 2025). A tumor composed of atypical neoplastic, often pleomorphic cells that invade other tissues. "Selenium-binding protein 1 (SELENBP1) has been implicated in cancer development, neurological disorders, tissue injury, metabolic regulation, and cell differentiation." (PMID 40298842, 2025). "The exact role of SELENBP1 is not well understood, with reduced levels associated with worse cancer prognosis." (PMID 38343831, 2024). "Consistent with this, a recent study showed that methanethiol is converted into dimethyl sulfide in cancer due to blockage of SELENBP1 (Selenium-binding protein 1) by mutation." (PMID 39840075, 2024). "Selenium is an essential nutrient with its utilization dependent on actions of the SELENBP1 gene which encodes a member of the selenium-binding protein relevant to preventions of some cancers and neurological diseases." (PMID 37915799, 2023). "Selenium exhibits potent anticarcinogenic properties, and its decreased SELENBP1 expression has often been associated with several cancer types." (PMID 36038612, 2022). "For example, Tff3, Hpse, Slit1, Spon1, Spock1, and Spock3 are associated with increased cancer cell invasion and were upregulated in Rreb1-/-, and Selenbp1 and Serpin6b are tumor suppressor genes that were downregulated." (PMID 33929320, 2021). "SELENBP1 is downregulated in many cancer types and its low expression levels are associated with poorer prognosis." (PMID 35141153, 2021). "Selenium-binding protein 1 (SELENBP1) expression is reduced markedly in many types of cancers and low SELENBP1 expression levels are associated with poor patient prognosis." (PMID 27583873, 2016). "In light of the compromised inflammatory processes with AD in microglia, SELENBP1 (Selenium Binding Protein 1) is a very intriguing gene, as failure to maintain sufficient selenium levels adversely affects immune responses and increases cancer risk 48–50." (PMID 38343831, 2024). "Moreover, reduced selenium-binding protein 1 expression is associated with poor outcome in various human cancers." (PMID 25227434, 2014). "Low SELENBP1 expression levels are associated with poor patient prognosis, clearly suggesting a role for SELENBP1 in regulating the growth and progression of cancer." (PMID 23704933, 2013). "Furthermore, reduced SELENBP1 was also associated with poor outcome and differentiation in lung, colorectal, ovarian, and prostate cancer." (PMID 23977169, 2013). "Furthermore, SELENBP1 has been shown to inhibit the progression of colon and prostate cancer via glucose/lipid metabolism and energy metabolism; it has also been linked to the survival of various cancers." (PMID 40298842, 2025). "In cancer treatment, genes Entpd1, Pgf, and Selenbp1 are being utilized as immunomodulatory targets." (PMID 38474724, 2024). "Another strong hint pointing to the dysregulation of methanethiol metabolism in cancer stems from observations that the methanethiol-degrading enzyme SELENBP1 is often and markedly downregulated in cancer tissue." (PMID 37760083, 2023). "SELENBP1, or Selenium Binding Protein 1, has been increasingly recognized in oncology circles for its nuanced role in cancer biology." (PMID 38357363, 2023). "Lowered expression of SELENBP1 has been reported for many types of cancer, such as tumors of the colon, lungs, ovaries, prostate, liver, thyroid, kidneys, and breast." (PMID 37760083, 2023). "Through a comprehensive analysis of multiple databases, we found that SELENBP1 was expressed at a low level in a variety of cancers." (PMID 36253721, 2022).
cancer (continued). "This leads to the usage of DNA methyltransferase and histone deacetylase to treat cancers targeting SELENBP1." (PMID 36386843, 2022). "We also discuss the potential cancer treatment targeting epigenetic modification of SELENBP1, either alone or in combination with selenium-containing compounds or dietary selenium." (PMID 36386843, 2022). "The methylation level of SELENBP1 promoter in CRC tissues was much higher than that in normal mucosa adjacent to cancer." (PMID 36253721, 2022). "The expression of SELENBP1 is significantly downregulated in various cancers, which means SELENBP1 plays an important role in cancer progression." (PMID 36386843, 2022). "To better understand the potential mechanisms of SELENBP1 in colorectal carcinogenesis, we investigated the relationship between SELENBP1 and 14 functional states of cancer in the CancerSEA database." (PMID 36253721, 2022). "The expression of SELENBP1 is downregulated in almost all cancers, indicating some suppressing functions of SELENBP1 in cancers." (PMID 36386843, 2022). "Epigenetic modification of SELENBP1 through promoter methylation in cancer has been demonstrated in many studies: DNA methylation at CpG islands in promoter regions is regulated by the DNA methyltransferase (DNMT) enzyme." (PMID 36386843, 2022). "The role of selenium in the precaution of carcinoma and neurological diseases perchance is regulated through selenium-united proteins, and alleviated expression of SELENBP1 presumably is relevant to a few kinds of cancer." (PMID 35710932, 2022). "Conversely, in human cancer cells, i.e., HeLa cells, in vitro knockdown of Selenbp1 by shRNA resulted in reduced sensitivity toward exogenous excess hydrogen peroxide." (PMID 34069420, 2021). "Collectively, these results demonstrate that SELENBP1 specifically up-regulates p21 protein levels and induces G0/G1 phase arrest, thereby leading to attenuation of cancer cell growth." (PMID 31918717, 2020). "The suppression of SELENBP1 in many other cancers was suggested to be involved in tumorigenesis and poor prognosis." (PMID 32443734, 2020). "Here, we establish a novel biochemical link between SELENBP1 and p21 protein, and further determine the indispensable role for p21 in SELENBP1-mediated growth inhibition in cancer cells." (PMID 31918717, 2020). "Selenium binding protein 1 (SELENBP1) has been known to be reduced in various types cancer, and epigenetic change is shown to be likely to account for the reduction of SELNEBP1 expression." (PMID 32443734, 2020). "To date, the molecular functions of SELENBP1 in cancer are relatively poorly understood, although it has been consistently reported to attenuate aberrant cell growth and suppress cell migration in a variety of cancer cells." (PMID 31918717, 2020). "Most studies with cancer cells generally report the methylation of selenoproteins like glutathione peroxidase 1 and 3, methionine sulfoxide reductase B1 and selenium binding protein 1 in the promoter region." (PMID 32722369, 2020). "The Se binding protein 1 (SELENBP1) gene and corresponding protein expression was found to be downregulated in Chinese CRC samples, as observed for the SELENBP1 mRNA levels in the cancer cohorts in this study." (PMID 30469315, 2018). "The results of IHC indicated that SELENBP1 expression in most of cancer nests is lower than in surrounding normal tissue." (PMID 27583873, 2016). "Kaplan–Meier analysis revealed prolonged cancer-specific survival in high-SELENBP1 expressors compared with low expressors in RCC (P = 0.014)." (PMID 25227434, 2014). "After adjusting for clinicopathologic variables, SELENBP1 expression (P = 0.006), N stage (P < 0.001), and T stage (P = 0.033) remained significantly correlated with cancer-related death in RCC." (PMID 25227434, 2014). "Decreased expression of selenium-binding protein 1 has been reported in cancers of the prostate, stomach, colon, and lungs." (PMID 21143902, 2010).
cancer (continued). "The anti-cancer action of selenium is thought to be mediated by selenium-binding protein 1 (SELENBP1), a 56 kDa intracellular protein, that binds covalently to selenium." (PMID 21143902, 2010). "It has been shown that selenium-binding protein 1 (SBP1) is significantly downregulated in different human cancers." (PMID 19924303, 2009). "Up to now, the previous studies have established an initial connection between SELENBP1 and human cancers, the expression of SELENBP1 was decreased in human cancer tissues including NSCLC, and the downregulated expression of SELENBP1 was associated with the progression and poor prognosis." (PMID 37606338, 2023). "Moreover, low SELENBP1 levels in cancer tissue correlate with poor clinical prognosis for the patients." (PMID 37760083, 2023). "SELENBP1 has roles in cellular redox modulation, cellular differentiation, metabolism of sulfur-containing protein, and intra-Golgi transport, and its expression is notably less in human cancer tissue compared with adjacent normal tissue." (PMID 37548833, 2023). "SELENBP1 is a special selenium-containing protein, which may play an anti-cancer role in a variety of cancer types, and its expression level in cancer is lower than that in corresponding normal tissue." (PMID 36253721, 2022). "Defects in this network can lead to cancer, while the mechanism of SELENBP1 in DDR during cancer was still unknown." (PMID 36386843, 2022). "SELENBP1 can be epigenetically modified through miRNA in cancer." (PMID 36386843, 2022). "We first assessed SELENBP1 expression in pan-cancer data from TCGA and GTEx." (PMID 36253721, 2022). "Reduced expression of selenium-binding protein 1 (SELENBP1), since first cloned in 1997, has been frequently observed in a variety of solid tumors, and is significantly related to unfavorable clinical outcome in multiple cancer types." (PMID 31918717, 2020). "Speculating that a SELENBP1 gene mutation could be responsible for the low expression levels, we studied the COSMIC (Catalogue of Somatic Mutations in Cancer)-home page." (PMID 29535818, 2018). "Kaplan–Meier estimates showed that low SELENBP1 expression was significantly correlated with cancer-specific death (log-rank test, P = 0.014), and a multivariate Cox regression model revealed that SELENBP1 expression was an independent predictor of cancer-specific death (HR, 0.111; P = 0.006)." (PMID 25227434, 2014). "SELENBP1 has been reported to be down-regulated in many types of cancers." (PMID 23704933, 2013). "SELENBP1 is identified as one of the candidate stromal epithelial cross-talk genes by analyzing common single-nucleotide polymorphisms (SNPs) for their association between the risk of serous ovarian cancer and telomerase reverse transcriptase (TERT), a cancer susceptibility “hot-spot”." (PMID 36386843, 2022). "However, SELENBP1 failed to modulate cancer cell growth in p21-deficiency cells, revealing that p21 protein serves as a crucial downstream mediator responsible for the growth-inhibitory role of SELENBP1 in cancer cells." (PMID 31918717, 2020). "To determine SELENBP1 expressions in cancer nests comparing with surrounding normal tissue, we chose 3 surrounding normal tissues as control, including normal nasopharyngeal mucosa, normal mucosa on the surface of cancer, and peripheral lymphoid tissue of the nests." (PMID 27583873, 2016). "Therefore, SELENBP1 may play a critical role in regulating malignant transformation and cancer progression." (PMID 25227434, 2014). "Therefore, reduced SELENBP1 may play a critical role in regulating malignant transformation and cancer progression." (PMID 23977169, 2013). "Therefore, SELENBP1 downregulation may play a critical role in regulating malignant transformation and cancer progression." (PMID 23977169, 2013).
cancer (continued). "SELENBP1 mRNA is abundantly expressed in many normal human tissues, while several groups have recently reported significantly decreased SELENBP1 protein levels in many types of cancers including lung, gastric, ovarian, colorectal and thyroid, compared to normal tissue." (PMID 23704933, 2013). "Many cancer-related genes, such as ZMYND8, ASAH1, and SELENBP1, were found mis-spliced following the degradation of RBM39." (PMID 40223119, 2025). "Under the conditions of low SELENBP1 and high METTL7B expression in cancer cells, METTL7B is then likely to catalyze the methylation of a part of the excessive methanethiol to DMS." (PMID 37760083, 2023). "Additional genes in this study, showing changes in gene expression for both the Irish and the Czech cancers were GPX2, GPX3, SELENOK, SEPHS2, SELENBP1, and SOD2." (PMID 30469315, 2018). "Given the cumulative data indicating possible roles of both SELENBP1 and GPX1 in cancer development and/or outcome, the interaction of these two selenium-associated proteins was investigated in several model systems." (PMID 29535818, 2018). "The results suggested that the expression levels of HLF, CHRDL1, and SELENBP1 in cancer tissues were significantly lower than those in normal tissues (p < 0.05)." (PMID 35205284, 2022). "Thus, GPX1, SELENBP1, SELENON, SELENOK, and SOD2 were differently expressed only in the cancer tissues." (PMID 30469315, 2018). "In our study, 99 patients of carcinoma were followed up in detail and these paraffin specimens were analyzed by IHC: SELENBP1 has negative expression in most of NPCs and the patients with negative expression have poor OS compared with positive expression." (PMID 27583873, 2016). "The present results suggest for the first time that downregulation of SELENBP1 may be involved in human RCC tumorigenesis and be an independent predictor of cancer-specific death in RCC." (PMID 25227434, 2014). "In conclusion, our study found that reduced SELENBP1 mRNA expression might play an important role in RCC tumorigenesis: low SELENBP1 mRNA expression correlates with aggressive disease and predicts cancer-specific survival in RCC." (PMID 25227434, 2014). "Although the molecular aspect of epigenetic changes of SELENBP1 in cancer remains largely unexplored and has not been used clinically in the diagnosis and treatments of patients with cancer yet, the prospects of novel discoveries and potential application of SELENBP1 are promising." (PMID 36386843, 2022).
infection (7 papers, 2013 to 2023). The state of being infected such as from the introduction of a foreign agent such as serum, vaccine, antigenic substance or organism. "The median [IQR] serum concentration of SELENBP1 at baseline was found to be considerably higher in the group of patients developing pulmonary infections than in burn patients without infections (45.6 [21.2–70.5] vs. 12.5 [3.7–34.2] μg/L; p = 0.007)." (PMID 38001780, 2023).
neurologic diseases (5 papers, 2016 to 2025). "Moreover, SELENBP1 has been identified as a biomarker for kidney injury, cardiovascular disease, and neurological disorders." (PMID 40298842, 2025).
neurodegenerative disease (3 papers, 2015 to 2023). A disorder of the central nervous system characterized by gradual and progressive loss of neural tissue and neurologic function. "Other music-related genes (GMPR, SELENBP1 and ADIPOR1) associated to neuropsychiatric, neurodegenerative diseases and music performance, emerged as hub genes in consensus co-expression modules detected between AD and music estimulated transcriptomes." (PMID 36819725, 2023).
psychiatric disorder (3 papers, 2012 to 2021). A disorder characterized by behavioral and/or psychological abnormalities, often accompanied by physical symptoms. "Considering that EDS patients suffer from psychiatric disorders, it would be interesting to dose SELENBP1 in serum EDS patients." (PMID 34576312, 2021).
adenocarcinoma (2 papers, 2022 to 2024). A common cancer characterized by the presence of malignant glandular cells. "Parallel to that, 5 proteins were expressed lower in SOL adenocarcinomas and the low expression of which was correlated with poor OS, including PIGR, CHDH, NAPSA, PLEKHA7 and SELENBP1." (PMID 38182978, 2024).
cardiovascular diseases (1 paper, 2022). "SELENBP1 involvement in cardiovascular diseases has not received attention until recently, where circulating levels of SELENBP1 have been found to associate with a risk for major adverse cardiac events and death." (PMID 36362053, 2022).
inflammation (1 paper, 2024). Aberrant reaction of the microcirculation characterized by movement of fluid and leukocytes from the blood into extravascular tissues. "Moreover, translational studies in the UC are needed since there is some evidence that SELENBP1 could play a role in the pathogenesis of intestinal inflammation in murine models and human IBD." (PMID 39728443, 2024).
respiratory disease (1 paper, 2011). "A subset of genes co-expressed with AQP4 and associated to respiratory disease were assigned to potential anti-tumorigenic function like CAV1, EDNRB, or SELENBP1, whereas genes more related to pro-tumorigenic function like CDK2, FOXM1, PLK1 or RRM1 were found to be anti-correlated with AQP4." (PMID 21548930, 2011).
SELENBP1 also shares sentences with these, for which no sentence is quoted: adenoma (2 papers); nasopharyngeal carcinoma (2); Parkinson’s (2); allergic disease (1); autoimmune disease (1); Bradycardia (1); brain disorder (1); cardiac arrest (1); cecum adenocarcinoma (1); Cognitive impairment (1); colon mucinous adenocarcinoma (1); colorectal tumor (1); Coronary Artery Diseases (1); dementia (1); depression (1); esophageal cancer (1); glioma (1); head and neck cancer (1); hypopharyngeal cancer (1); injury (1); Insulin resistance (1); invasive ductal carcinoma (1); kidney cancer (1); laryngeal carcinoma (1); Larynx (1); metastatic melanoma (1); movement disorder (1); nicotine dependence (1); non-small cell lung carcinoma (1); oral cancer (1).
A further 12 diseases each share a sentence with SELENBP1 in 1 paper.